IL10 (interleukin 10)
Diseases named in the same sentence as IL10 in open-access papers (continued):
Sharing a sentence is not in itself a finding about the gene and the disease.
autoimmune disease (continued). "An interesting study performed by Meng and colleagues demonstrated that HIF-1α contributes to IL-10 production by CD1dhi CD5+ B cells, as it directly regulates IL-10 expression during autoimmune disease." (PMID 31086070, 2019). "For example, in autoimmune diseases including SLE and rheumatoid arthritis, IL-10-producing (IL-10+) Bregs have been shown to be functionally impaired and decreased in numbers." (PMID 31519970, 2019). "Previous reports on IL-10+ CD138+ plasmablasts and plasma cells in LN and spleen indicate that these cells are formed in the course of autoimmune diseases or infections and exhibit the capacity to limit the inflammatory reaction accompanying these conditions." (PMID 31214168, 2019). "Although the reason why clinical trials of IL-10 supplementation in autoimmune diseases are largely ineffective remains unclear, it is considered that the effects of IL-10 seem to be quite complex and further clinical and experimental studies are needed for clinical application of IL-10." (PMID 29765083, 2018). "MSCs producing anti-inflammatory cytokines, such as IL-10 and TGF-β, have been tested in autoimmune disease models." (PMID 30013550, 2018). "Our findings indicate that IL-10 act as a negative regulator of IL-33/ST2 signaling pathways in vivo, suggesting a potential therapeutic role of IL-10 in autoimmune diseases." (PMID 28415811, 2017). "Treg, on the other hand, counters the proliferation and activation of effector T cells via suppressing cytokines such as IL-10 and TGF-β, so as to maintain tolerance to self-antigens, and prevent autoimmune disease." (PMID 29204117, 2017). "B cells, identified by releasing IL-10, IL-35, and TGF-β, had been shown to limit inflammation, autoimmune disease, and tumor, while B cells, identified by secreting TNF-α, IL-6, and GM-CSF, had been shown to promote disease." (PMID 28831210, 2017). "Lately, the impact of regulatory B cells (Bregs), functionally characterized by their IL-10 and TGF-β production, has been highlighted in etiopathogenesis of autoimmune diseases, including SLE." (PMID 28846748, 2017). "Regulatory T cells (Tregs) play a role in the suppression of inflammation in autoimmune diseases, and lymphocyte activation gene 3 (LAG3) was reported as a marker of interleukin (IL)-10-producing Tregs." (PMID 28511719, 2017). "IL-10-expressing B cells were previously demonstrated to suppress CD8+ T cell inflammation in HIV and HBV infections, autoimmune diseases, and tumor." (PMID 27136203, 2016). "Non-classical MHC class Ib (Qa-1)-restricted CD8αα+ T cells can repress autoimmune diseases by not only direct killing of effector T cells via perforin but also with the help of immunosuppressive cytokines such as TGF-β and IL-10." (PMID 26908454, 2016). "Interleukin-10 (IL-10) and tumor necrosis factor (TNF) are key cytokines that have been intensively investigated in autoimmune diseases and malignancies." (PMID 26108796, 2015). "The other major regulatory T-cell subset denoted as IL-10 producing Type-1 regulatory T cells (CD4+IL-10+, Tr1) has been investigated and found to have an important role in the development of various autoimmune diseases." (PMID 26300591, 2015). "Although this particular B cell regulatory effect was not IL-10 dependent, various mouse models have reinforced the importance of B cell derived IL-10 in EAE and other human autoimmune disease." (PMID 25002862, 2014). "Thus when IL-10 production is decreased by inhibition of Tr1 differentiation, lung inflammation induced by M. pneumoniae antigens cannot be mitigated, and extrapulmonary complications similar to autoimmune diseases may also occur in vivo." (PMID 24928272, 2014). "Previous studies have shown that IL-10 and TGF-β have anti-inflammatory and protective effects in a variety of autoimmune diseases." (PMID 23738007, 2013).
autoimmune disease (continued). "In a number of autoimmune disease conditions in animals and in humans, IVIG has been shown to induce the expansion of Tregs and IL-10 secretion; dendritic cell processing is required for the effect of IVIG in some studies." (PMID 23710469, 2013). "These IL-10 secreting B cells can suppress CD4+ T cell responses and prevent autoimmune disease in mouse models and have been fittingly named regulatory B cells or Bregs." (PMID 23807906, 2012). "Additionally, IL-10 induces the formation of T regulatory-1 cells, and this should also drive the immune response towards active rather than a passive tolerance, which should in turn provide a more robust and long-lasting protection from the onset of the autoimmune disease." (PMID 19298643, 2009). "Attenuation of the IL-10 and transforming growth factor-β (TGF-β) effect has been shown to result in inflammation and the onset of autoimmune diseases." (PMID 16759382, 2006). "Furthermore, in an autoimmune disease model, CD122+CD8+ Treg cells prevented the development of disease through IL‐10‐mediated suppression of IL‐17 production." (PMID 40629997, 2025). "MS is an autoimmune disease induced by autoreactive T lymphocytes that is characterized by an imbalance of pro-inflammatory cytokines, such as TNF, interferon γ (IFN-γ), IL-2 and lymphotoxin, and regulatory cytokines (e.g., IL-4 and IL-10)." (PMID 40076462, 2025). "Contrary to findings in autoimmune disease and cancer, the blockade of LAG-3 increased the production of Th1-type tumor necrosis factor (TNF)-α and interferon (IFN)-γ, but decreased Th2-type and Treg-type IL-4, IL-10 and transforming growth factor (TGF)-β1." (PMID 41023624, 2025). "Applying anti-IL-10 antibody or scFv secretion from a CAR Treg would likely have anti-inflammatory effects similar to an anti-IL-6 secreting Treg, but with the potential for further implementation in a wider variety of autoimmune diseases." (PMID 39445021, 2024). "In the case of IL-10, is it not quite clear how autoimmune diseases and especially SLE are associated, since other investigators showed significant aggravation of autoimmune diseases upon IL-10 absence." (PMID 39456692, 2024). "Different subtypes of Transitional B cells also have different functions, for example, the T2/T3 type produces IL-10 to reduce CD4+ T-cell proliferation but, in some autoimmune diseases, Trb also secretes anti-inflammatory factors (IL-6 and TNF-α) that disrupt the Treg/Th17 balance." (PMID 38812518, 2024). "IL-10 is highly elevated in CRS and in many autoimmune diseases." (PMID 39445021, 2024). "MS is an autoimmune disease induced by autoreactive T-lymphocytes that is characterized by an imbalance of pro-inflammatory cytokines, such as TNF-α, IFN-γ, IL-2 and lymphotoxin, and regulatory cytokines (e.g., IL-4 and IL-10)." (PMID 39596101, 2024). "TGF-β-producing B cells have been shown to regulate the immune response independent of IL-10 in various inflammatory diseases, including autoimmune diseases, cancer, and allergies." (PMID 37180165, 2023). "Furthermore, we discuss the clinical applications of the IL-10:TNF-α ratio, using it as an predictor of pro- and anti-inflammatory treatment outcomes in autoimmune diseases and transplantation." (PMID 37180165, 2023). "While IL-6 expression in VR increases, in parallel with IL-10 suppress EAO development, it can reduce TGC-induced EAO, and triggers apoptosis of germ cells within seminiferous tubules, known to exert opposite effects in autoimmune diseases." (PMID 37048754, 2023). "However, Th 17 cells and their related cytokines, such as IL-6, IL-10, IL-17 and TNF-α, are important inflammatory mediators in autoimmune diseases, including uveitis, and are thought to drive intraocular inflammation." (PMID 38351911, 2023). "Various attempts to positively influence autoimmune diseases, such as multiple sclerosis, by administration of IL-10 did not demonstrate a clear effect." (PMID 35625063, 2022).
autoimmune disease (continued). "In autoimmune diseases, Tregs inhibit DC maturation and improve immune tolerance by secreting IL-10/TGF-β/IL-35; moreover, DC provides conditions for Treg cell generation via the production of IL-10/TGF-β/IL-35." (PMID 36177043, 2022). "Nonetheless, the expression of IL-10 can be aberrant in patients with autoimmune diseases, including D-IBS that may lower the IL-10 level in plasma." (PMID 36438735, 2022). "Studies have shown that Treg cells prevent the occurrence of autoimmune diseases critically depending on the effect factors TGF-β and IL-10, while Th17 cells promote autoimmune and inflammatory processes mainly by secreting IL-17A closely involved with the severity of IBDs." (PMID 36304936, 2022). "Although a direct relationship between HCMV, IL-10, and autoimmune disorders has not yet been recognized, further investigations are needed to better clarify a possible role of HCMV cytokine homologs in these diseases." (PMID 33567734, 2021). "Since cytokine IL-10 and B. bifidum BGN4 have been applied in various fields, they have also shown potential in treating human autoimmune diseases such as inflammatory bowel disease (IBD), cancer, rheumatoid arthritis, and in the prevention of obesity and allergies." (PMID 33468130, 2021). "Some studies of autoimmune diseases have reported that MSC-EVs drive a shift from Th1 toward Th2 cells and rebalances Th1/Th2 cells by downregulating proinflammatory cytokines TNFα and IFNγ and upregulating anti-inflammatory cytokines IL-10 or IL-4." (PMID 34447855, 2021). "It has been reported that α-GalCer stimulation can induce iNKT cells to produce both anti-inflammatory cytokines (e.g., IL4, IL13, and IL10) and pro-inflammatory cytokines (e.g., IFNγ, TNFα, and IL17), ultimately determining the outcome of autoimmune diseases such as EAE." (PMID 30766446, 2019). "Taken together, by enhancing IL-10 production and suppressing Th17 cells, the SCFA pentanoate might be of therapeutic relevance for inflammatory and autoimmune diseases." (PMID 30770822, 2019). "However, for active autoimmune diseases such as SLE, due to the significant increase in IL-10 expression, its role in promoting plasma cell differentiation is dominant, which in turn promotes immune disorders." (PMID 31240224, 2019). "Even though these individuals were not diagnosed with autoimmune disease or depression, IL-10 concentrations still correlated with depressive symptoms, although the association was not terribly strong (p = 0.047, OR = 1.05)." (PMID 30148175, 2018). "This change in the balance of IFNγ to IL-10 has been observed in other autoimmune diseases, but has not been previously reported for AIR." (PMID 30271775, 2018). "Although B-1a cells are associated with the regulation of autoimmune disease through the secretion of anti-inflammatory cytokines, the CD3+ B-1a cells did not secrete IL-10." (PMID 30670930, 2018). "We investigated whether blocking IL-10 at the time of immunization results in intestinal inflammation responses in a mouse TC-1 tumour model and in a NOD autoimmune disease prone mouse model." (PMID 28810829, 2017). "IL-10--producing B cells, Foxp3-expressing T cells (Tregs) and the IDO-expressing dendritic cells (pDC) are able to modulate inflammatory processes, to induce immunological tolerance and, in turn, to inhibit the pathogenesis of autoimmune disease." (PMID 23800367, 2013). "Pro-inflammatory cytokines, such as TNF or IL12A, the T-cell activation molecule CD28, the regulatory molecules IL10, TGFB1 or the adhesion molecules ITGA4 and ITGB1 have all been evaluated previously as therapeutic targets for autoimmune diseases, including MS." (PMID 18030350, 2007). "To date, no IL-10–centric treatment has yet been approved for AS or other autoimmune diseases." (PMID 41009491, 2025). "Thus, it can be speculated that the increase in IL-10 due to MSCT could serve an immunomodulatory role or help correct Th1 and Th2 imbalance in Th1-predominant autoimmune diseases." (PMID 39273184, 2024).
autoimmune disease (continued). "The suppressive capacity of IL10+ regulatory B cells has been reported to be diminished or absent in patients with various autoimmune diseases, suggesting that decreased IL10 expression may be a critical factor in the pathogenesis of these disorders." (PMID 39337678, 2024). "Therefore, there is no protective role of the Th2 response in these autoimmune diseases, and even increased IL-10 in both autoimmune diseases accelerates autoimmune destruction." (PMID 35894054, 2022). "On further adjusted analyses, stratified by the level of expression of specific cytokines in autoimmune diseases, 30-day mortality was reduced in those autoimmune diseases with overexpression of IL-1, IL-6, IL-12, IFN-γ, and TNF-α, as well as in those with reduced expression of IL-4 and IL-10." (PMID 35271683, 2022). "However, the application of IL-10 for the treatment of autoimmune diseases has not been successfully translated into clinical practice because of its short half-life in vivo." (PMID 35255957, 2022). "The presence of rare variants in these genes might play a crucial role in the development of the autoimmune diseases due to their complex interactions in key related pathways regulating receptor binding and FCGR3A-mediated IL10 synthesis, which is an important immunoregulatory cytokine." (PMID 35783297, 2022). "Our results suggest that SLAMF5 is a negative moderator of IL-10+ Breg cells, and may serve as a therapeutic target in MS and other autoimmune diseases." (PMID 33767202, 2021). "Although it is unclear whether the therapeutic effect is mediated by IL-10 or not, our study may benefit the future clinical application of B10 cells in the immunotherapy of inflammatory and autoimmune diseases." (PMID 34099635, 2021). "IL-10–producing Th17 cells are indicative of the nonpathogenic Th17 cell population that has been shown to have a critical role in restraining Th17 cell–mediated inflammatory and autoimmune diseases." (PMID 30598515, 2019). "This could explain why IVIg is effective for a diverse range of inflammatory and autoimmune diseases, as IL-10 has a critical, non-redundant role in turning off both innate and adaptive immune signaling and restoring tissue homeostasis." (PMID 30515163, 2018). "Moreover, immunization with papillomavirus like particles combined with simultaneously blocking IL-10 signalling does not increase the incidence of autoimmune disease in Non-obese diabetic (NOD) mice." (PMID 28810829, 2017). "Furthermore, when those 7 patients with autoimmune disease were excluded from our analysis, the results of ROC analysis for IL-10 did not change significantly (AUC = 0.807, p < 0.001)." (PMID 28432351, 2017). "In addition to the regulatory effects of FoxP3+ and FoxP3− Tregs, an IL-10-dependent negative feedback loop is important in protecting tissues from T cell-mediated autoimmune disease and infection-driven immunopathology." (PMID 23755052, 2013). "Flow cytometry analysis of the composition of T-cells producing IFN-γ (Th1), IL-17A (Th17), IL-4 (Th2), and IL-10 (Treg) revealed no visible changes in the percentage of Th1 and Treg cells in response to various exosomes for both MS patients and control subjects without autoimmune disease." (PMID 37108633, 2023). "Besides those protocols aimed at preparing tolerogenic DC by incubation with IL-10 in the therapy of autoimmune diseases, which are not the scope of this Minireview, there are also inflammatory conditions where induction of IL-10 takes place and results in similar suppressive functions." (PMID 30233565, 2018). "Stronger T cell responses without IL-10 may induce autoimmune diseases in vaccinated patients." (PMID 28810829, 2017). "Elevated IL-8, IL-10, IL-1β, and TNF-α levels have been reported in subclinical hypothyroid HT patients, though this study did not assess concurrent autoimmune diseases or the potential adverse metabolic impact of hypothyroidism." (PMID 39518417, 2024).
autoimmune disease (continued). "Importantly, our observation that B cells from active-disease mice exhibited decreased numbers but not decreased IL-10 production by MZ B cell subsets as compared to pre-disease mice suggests that this subset may be particularly important to control autoimmune disease pathogenesis in this model." (PMID 38155972, 2023). "VD3 was shown to induce a non-specific up-regulation of IL-10 and TGF-β and of Tregs also in an experimental autoimmune disease model." (PMID 27499704, 2016). "Moreover, we show that while CTLA-4, but not IL-10, plays a role in the induction of Foxp3 expression in naive CD4+ T cells, the latter is important for iTreg cell-mediated protection from autoimmune disease." (PMID 25238105, 2014). "Interestingly, co-transfer of regulatory T cells (IL-10 and TGF-β secreting) was capable of reducing the incidence and severity of this autoimmune disease in Th1 and Th2 injected mice, but not in the Th17 injected group." (PMID 19622600, 2011). "Indeed, several negative feedback mechanisms such as secretion of IL10, IDO1 and TGFβ are induced during immune activation to maintain homeostasis and prevent excessive immune responses that could lead to tissue damage or autoimmune diseases." (PMID 40756372, 2025).